YTHDF1 (YTH N6-methyladenosine RNA binding protein F1)
Diseases named in the same sentence as YTHDF1 in open-access papers (continued):
Sharing a sentence is not in itself a finding about the gene and the disease.
colorectal adenocarcinoma (1 paper, 2024). The most common type of colorectal carcinoma. "Notably, YTHDF1 exhibits high expression levels in colorectal adenocarcinoma, lung adenocarcinoma (LUAD) and colorectal adenocarcinoma tissues, while YTHDF2 is notably up‐regulated in breast cancer (BRCA), head and neck squamous cell carcinoma (HNSC), LUAD and prostate cancer (PRAD)." (PMID 39135292, 2024).
dilated cardiomyopathy (1 paper, 2026). Cardiomyopathy which is characterized by dilation and contractile dysfunction of the left and right ventricles. "Human left ventricle (LV) exhibited higher YTHDF1 expression than right ventricle (RV), while LV from dilated cardiomyopathy (DCM) patients showed modestly reduced YTHDF1 levels compared to healthy controls." (PMID 42139185, 2026).
dry eye (1 paper, 2023). "Our findings revealed that the expression level of the m6A modification and the mRNA and protein expression of METTL3 and YTHDF1 were all increased in pSS patients with dry eye." (PMID 37277716, 2023).
endometrial adenocarcinoma (1 paper, 2021). "In the present research, we elucidated that m6A RNA methylation regulators, especially FTO, RBM15, and YTHDF1, were likewise closely related with prognosis of endometrial adenocarcinoma." (PMID 34149936, 2021). "In conclusion, m6A methylation regulators, especially FTO, RBM15, and YTHDF1, are critical in the progression and prognosis of endometrial adenocarcinoma." (PMID 34149936, 2021). "Finally, we validated the mRNA expression of METTL3, FTO, RBM15, and YTHDF1 in clinical samples of endometrial tissues from endometrial adenocarcinoma patients and controls." (PMID 34149936, 2021). "The expression of YTHDF1, YTHDF2, and IGF2BP1/2 was increased in women with endometrial adenocarcinoma, whereas a reduction in YTHDC1 was detected." (PMID 34149936, 2021). "Hence, FTO, RBM15, and YTHDF1 may regulate the RNA processing and translation of target genes involved in the cell cycle, thermogenesis and other pathways, leading to the tumor process and prognosis of endometrial adenocarcinoma." (PMID 34149936, 2021). "We found that METTL3 and FTO mRNA expression was evidently decreased in endometrial adenocarcinoma while RBM15 mRNA expression was increased with no changes in YTHDF1 expression in cases versus controls." (PMID 34149936, 2021).
Fanconi anaemia (1 paper, 2024). "KEGG enrichment analysis showed that YTHDF1 was positively correlated with the cell cycle, Fanconi anaemia pathway and homologous recombination." (PMID 38683130, 2024).
Fulminant hepatitis (1 paper, 2023). Acute hepatitis complicated by acute liver failure with hepatic encephalopathy occurring less than 8 weeks after the onset of jaundice. "Thus, we hypothesized that YTHDF1 protects against fulminant hepatitis and investigated the underlying molecular mechanisms." (PMID 37564203, 2023). "In the current study, YTHDF1 expression was found to be significantly downregulated in the livers among patients, as well as murine models with fulminant hepatitis versus normal controls." (PMID 37564203, 2023).
gallbladder cancer (1 paper, 2024). "The current study seeks to investigate the function of YTH m6A RNA‐binding protein 1 (YTHDF1) in gallbladder cancer." (PMID 38683130, 2024). "FFPE sections with gallbladder cancer (GBC) were evaluated to determine the mean optical density (MOD) of anti‐YTHDF1 immunohistochemical staining." (PMID 38683130, 2024). "Collectively, these findings provide new insights into the progression of gallbladder cancer as well as a novel post‐transcriptional mechanism of YTHDF1 via stabilizing target mRNA." (PMID 38683130, 2024). "Transcriptomic analysis and immunochemical staining of YTHDF1 in gallbladder cancer tissues revealed its upregulation compared to paracancerous tissues." (PMID 38683130, 2024). "Moreover, YTHDF1 promotes the proliferation assays, Transwell migration assays, and Transwell invasion assays of gallbladder cancer cells in vitro." (PMID 38683130, 2024). "In this study, we suppose to investigate the clear functions of YTHDF1 and m6A‐dependent functions on regulating m6A/UHRF1 axis in gallbladder cancer progression." (PMID 38683130, 2024).
gastric cardia adenocarcinoma (1 paper, 2021). A carcinoma that arises from glandular epithelial cells of the cardia of stomach. "Furthermore, YTHDF1 expression was significantly increased both in gastric cardia adenocarcinoma (GCA) and gastric non-cardia adenocarcinoma (GNCA) according to the GSE29272 dataset compared with their pair-matched normal tissues." (PMID 33791305, 2021).
gastrointestinal stromal tumor (1 paper, 2023). "In gastrointestinal stromal tumors (GIST), YTHDF1 forms a complex with eEF-1 (eukaryotic elongation factor-1) and promotes the translation of MRP1 mRNA in an m6A-dependent manner." (PMID 38202722, 2023).
HCMV infection (1 paper, 2022). "It was observed that the mRNA levels of METTL3, METTL14, YTHDF1, YTHDF2, and YTHDF3 were significantly increased in HAECs following HCMV infection." (PMID 35359726, 2022).
Hepatic steatosis (1 paper, 2026). Steatosis is a term used to denote lipid accumulation within hepatocytes. "Under high-fat diet intervention, hepatocyte-specific Ythdf1-knockout mice exhibited a pronounced increase in both liver weight and liver-to-body weight ratio, accompanied by significant hepatic steatosis." (PMID 41963469, 2026).
Hepatitis (1 paper, 2025). Inflammation of the liver. "Indeed, bone marrow transplantation analysis supported that YTHDF1 deficiency in hematopoietic cells is the origin of the hypersensitive response during ConA-induced hepatitis." (PMID 40092485, 2025). "Our study further supports the critical role of YTHDF1 in suppressing inflammation during T cell-mediated hepatitis." (PMID 40092485, 2025). "Collectively, these data demonstrate that YTHDF1 deficiency exacerbates the cytokine storm and hepatic inflammatory response, mainly through ERK and NF-κB pathways in ConA-induced hepatitis." (PMID 40092485, 2025). "In summary, our study uncovered that YTHDF1 deficiency exacerbates the immune response in ConA-induced hepatitis by modulating the expression of inflammatory mediators, highlighting the potential of YTHDF1 as a therapeutic target for clinical hepatitis." (PMID 40092485, 2025). "Validation in bone marrow chimeric mice confirmed the necessity of YTHDF1 in hematopoietic cells for controlling the response to ConA-induced hepatitis." (PMID 40092485, 2025). "Overall, our results underscore the pivotal role of YTHDF1 in ConA-induced hepatitis, positioning it as a promising therapeutic target for immune-mediated hepatitis." (PMID 40092485, 2025). "In conclusion, the rapid turnover of YTHDF1, YTHDF2, and YTHDF3 proteins during early ConA-induced hepatitis emerges as a hallmark of risk, suggesting their potential as crucial inflammation indicators in immune-mediated hepatitis." (PMID 40092485, 2025). "Despite a dramatic decrease in hepatic YTHDF1 protein during ConA-induced hepatitis, specific over-expression, or knockout in hepatocytes may not affect hepatic damage or cytokine release, implying redundancy." (PMID 40092485, 2025). "However, the precise role of YTHDF1 in T cell-mediated hepatitis remains incompletely characterized." (PMID 40092485, 2025). "Because of the observations in the dramatic decrease and subsequent increase in hepatic YTHDF1 protein during the early and late stages of ConA-induced hepatitis, we investigated the involvement of YTHDF1 in hepatocytes in the ConA-mediated inflammatory storm and hepatotoxicity." (PMID 40092485, 2025). "However, further research using T cells conditional knockout of YTHDF1 is warranted for exploring its role in T cell-mediated hepatitis." (PMID 40092485, 2025). "Therefore, we hypothesized that YTHDF1 deletion in macrophages would enhance inflammatory responses, mirroring aggravated ConA-induced hepatitis in Ythdf1−/− mice and bone marrow chimeric mice." (PMID 40092485, 2025). "KEGG pathway analysis of differentially expressed genes between Ythdf1−/− mice and WT mice indicated enrichment in IL-17 signaling, Th1/Th2 cell differentiation, and Th17 cell differentiation, suggesting that YTHDF1 deficiency affects the T cell function in ConA-induced hepatitis." (PMID 40092485, 2025). "Initially, we investigated the protein expression of m6A readers, YTHDF1, YTHDF2, and YTHDF3, during the early stage of ConA-induced hepatitis and found that they were dramatically decreased in the liver." (PMID 40092485, 2025). "This suggests that hepatic YTHDF1 does not impact hepatocyte death or T cell activation-mediated inflammatory storms in ConA-induced hepatitis." (PMID 40092485, 2025). "Surprisingly, hepatic-specific knockout or overexpression of YTHDF1 showed no significant impact on hepatic injury and cytokine release, suggesting a redundant role of YTHDF1 in hepatocytes during ConA-induced hepatitis." (PMID 40092485, 2025). "Notably, the deficiency of YTHDF1, but not YTHDF3, exacerbated hepatic injury, marked by heightened cytokine production and inflammatory cell infiltration during ConA-induced hepatitis." (PMID 40092485, 2025). "Indeed, unlike the liver in ConA-induced hepatitis, the LPS challenge increased both YTHDF1 protein and mRNA levels in PM, indicating YTHDF1's potential role as an inflammatory regulator." (PMID 40092485, 2025).
intestinal cancer (1 paper, 2023). "In addition, since YTHDF1 upregulation is observed in both human and mouse intestinal cancer, YTHDF1 may behave as a biomarker for CRC21." (PMID 37872148, 2023).
irritable bowel syndrome (1 paper, 2024). Irritable bowel syndrome (IBS) is a chronic functional condition of the lower gastrointestinal (GI) tract characterized by abdominal pain or discomfort and disordered bowel habit (diarrhea, constipation, or fluctuation between the two). "As a treatment for irritable bowel syndrome with constipation, compound 48 (Tegaserod, YTHDF1 IC50 = 13.82 μM) was recently reported as a novel potential YTHDF1 inhibitor, which prevents YTHDF1 from binding m6A modified mRNA and YTHDF1 dependent protein translation." (PMID 38711100, 2024).
ischemic stroke (1 paper, 2025). A stroke disorder caused by obstruction of blood flow to the brain, due to thrombotic (local blood clot formation) or embolic (due to a blood clot or other material traveling from another site) event.
lupus (1 paper, 2025). "This hypothesis is further supported by mouse experiments demonstrating that the deficiency of Ythdf1 substantially impedes the expression of Irf4, diminishes the proportion of PCs and ameliorates the lupus-like phenotypes." (PMID 41258073, 2025). "Depletion of YTHDF1 hindered the differentiation of PCs, reduced the generation of autoantibodies and ameliorated the lupus-like phenotypes in an imiquimod-treated mouse model." (PMID 41258073, 2025). "The conditional knockout of Ythdf1 in B cells resulted in a decrease in the generation of autoantibodies and an improvement in the lupus-like phenotypes in mice." (PMID 41258073, 2025).
muscle degeneration (1 paper, 2025). "Our data reveal Ythdf1 as a key regulator of skeletal muscle homeostasis, provide insights into the mechanism by which endurance exercise promotes skeletal muscle remodeling and highlight potential strategies to prevent aging-related muscle degeneration." (PMID 39948064, 2025).
non-alcoholic steatohepatitis (1 paper, 2025). "In non-alcoholic steatohepatitis-associated HCC (NASH-HCC), YTHDF1 was targeted by lipid nanoparticles (LNPs)-encapsulated small-interfering YTHDF1, which can promote antitumor immunity by suppressing EZH2-IL-6 axis." (PMID 40958857, 2025).
osteoarthritis (1 paper, 2025). A noninflammatory degenerative joint disease occurring chiefly in older persons, characterized by degeneration of the articular cartilage, hypertrophy of bone at the margins and changes in the synovial membrane. "Moreover, METTL3-mediated m6A modification decreases PRDX3 mRNA stability by YTHDF1 in the osteoarthritis cartilage injury model." (PMID 40757971, 2025).
Peri-Implantitis (1 paper, 2023). An inflammatory process with loss of supporting bone in the tissues surrounding functioning DENTAL IMPLANTS. "Taken together, the results indicate that m6A modification of mRNA plays a vital role in MC3T3-E1 cells under hypoxia, and YTHDF1 with its downstream THBS1 might provide potential candidates for the treatment of hypoxia-induced bone loss in peri-implantitis." (PMID 36675257, 2023). "Our findings revealed the role of YTHDF1 in regulating the osteogenesis of MC3T3-E1 cells and suggested that YTHDF1 may be a potential therapeutic target for peri-implantitis treatment." (PMID 36675257, 2023). "To investigate the role of YTHDF1 in peri-implantitis, we retrieved microarray data related to peri-implantitis using the gene expression omnibus (GEO) database and finally obtained GSE33774 microarray data, which showed a significant increase in YTHDF1 expression in peri-implantitis tissue." (PMID 36675257, 2023). "According to the findings of our results, we hypothesized that YTHDF1 regulates Thrombospondin-1 (THBS1) post-transcriptionally through m6A methylation to promote osteogenic differentiation of MC3T3-E1 cells, providing an important potential for the treatment of peri-implantitis." (PMID 36675257, 2023). "The limitation of our study is that the downstream targets of YTHDF1 may not be limited to THBS1, and further studies that explore other downstream targets of YTHDF1 are required for a better understanding of the role of YTHDF1 in the pathogenesis of peri-implantitis." (PMID 36675257, 2023).
Pleural effusion (1 paper, 2020). The presence of an excessive amount of fluid in the pleural cavity. "In addition, based on a GEO dataset (GSE79637) of HNSCC specimens, YTHDF1 expression was more prominent in highly metastatic lines (FaDu origin: hypopharynx, Detroit 562 origin: pleural effusion) than in nonmetastatic lines (YCU-OR891 origin: oral floor, YCU-MS861 origin: maxillary sinus)." (PMID 33204330, 2020).
prostate tumors (1 paper, 2022). "Next, we analyzed the correlation between YTHDF1 expression and clinicopathological characteristics of prostate tumors." (PMID 36439881, 2022). "Expression of YTHDF1 was also evaluated in human prostate tumors and either adjacent or paired normal tissues." (PMID 36439881, 2022).
psoriasis (1 paper, 2025). An autoimmune condition characterized by red, well-delineated plaques with silvery scales that are usually on the extensor surfaces and scalp. "The results of single‐cell RNA sequencing in the lesions of psoriasis patients and RNA sequencing in BMDMs revealed that YTHDF1 and IGF2BP2 were expressed in macrophages." (PMID 40679079, 2025).
pulpitis (1 paper, 2023). Inflammation of the dental pulp. "The results showed that there were significant differences in the genes ALKBH5, METTL14, METTL3, METTL16, RBM15B and YTHDF1 between normal group and the pulpitis group." (PMID 37978362, 2023). "However, YTHDF1, YTHDF3, METTL16 and METTL3 gene expression were not statistically different between the pulpitis group and the control group, and RBM15B, ZCCHC4 and ALKBH5 were up-regulated." (PMID 37978362, 2023).
rectal tumors (1 paper, 2021). "The significant up-regulation of YTHDF1, YTHDF2, and METTL3, and down-regulation of ALKBH5, YTHDC2, and METTL14 could be observed in the 6 rectal tumors (P < 0.05), indicating that these m6A regulators may be associated with progression of RC." (PMID 34149792, 2021).
skin cancer (1 paper, 2020). "Therefore, we assessed expression level of YTHDF1 and its major paralog YTHDF2 across other types of skin cancer to investigate whether this family of genes is essential for all cancer cells or it is a unique feature in MCC." (PMID 31947544, 2020).
viral hepatitis (1 paper, 2025). An acute or chronic inflammation of the liver parenchyma caused by viruses. "Despite advances in understanding canonical m6A readers such as YTHDF1–3 and YTHDC1/2, the functions of noncanonical readers – such as IGF2BP1–3, HNRNPC, and HNRNPG remain largely unexplored in the context of viral hepatitis." (PMID 40793828, 2025).